HSF1 (heat shock transcription factor 1)
Diseases named in the same sentence as HSF1 in open-access papers (continued):
Sharing a sentence is not in itself a finding about the gene and the disease.
heart failure (continued). "HSF1 has been identified to suppress IGF-IIR expression to protect cardiomyocytes, we assumed that the dysregulation of the HSF-IGF-IIR participates in DOX-induced heart failure." (PMID 27809308, 2016). "HSF1 and ALDH2 are potential endogenous cardioprotective factors, and there are already lots of evidences for their cardioprotective effect, but it is not yet reported whether HSF1 can regulate ALDH2 to delay the occurrence of heart failure." (PMID 32626739, 2020). "Evidences abound that HSF1 and ALDH2 are of cardioprotective effect, yet there is still no report on whether HSF1 can regulate ALDH2 to delay the occurrence of heart failure." (PMID 32626739, 2020).
Insulin resistance (9 papers, 2017 to 2025). Increased resistance towards insulin, that is, diminished effectiveness of insulin in reducing blood glucose levels. "Available studies suggest that HSF1 has multiple roles, both in preventing insulin resistance and in inhibiting glycolipotoxicity-induced β-cell apoptosis." (PMID 40878475, 2025). "Reduced levels of HSP70 and its transcription factor (HSF1) correlated with insulin resistance and NAFLD progression." (PMID 38132434, 2023). "The high expression of HSF1 may exacerbate insulin resistance by enhancing the production of these pro-inflammatory factors, thereby increasing the risk of T2DM." (PMID 40878475, 2025). "It has been demonstrated that reduced activity of the anti-inflammatory HSP70 pathway correlates with nonalcoholic fatty liver disease (NAFLD) progression and with markers of oxidative stress in the obese patient, paralleled by similar reductions in HSF1 and insulin resistance." (PMID 36978903, 2023). "Therefore, we hypothesised that circadian rhythm disruption may lead to abnormal activation of HSF1, affecting the expression of HSPs, resulting in insulin resistance and pancreatic islet cell dysfunction." (PMID 40878475, 2025). "BGP-15, a nicotinic kainamide oxime derivative, directly activates HSF1 and promotes HSP70 expression, thereby improving insulin resistance and mtBE." (PMID 41488136, 2025).
proteinopathies (9 papers, 2010 to 2021). "The failure of the proteostasis network to maintain aggregation-prone proteins in their soluble-state is a major pathogenic mechanism underlying HD and other protein-folding diseases, for which the development of therapeutics to boost proteostasis capacity by targeting HSF1, has been proposed." (PMID 33907289, 2021). "Given its various significant functions, loss of HSF1 may underlie a fundamental mechanism of neurodegeneration, featured by proteinopathies." (PMID 26503960, 2016). "In summary, we discovered complete loss of HSF1 protein under various conditions of proteinopathies, suggesting that aberrant HSF1 protein degradation may represent a common and important key molecular mechanism underlying neurodegeneration." (PMID 26503960, 2016). "For example, our data has shown that the loss of S303-dependent HSF1 repression can lead to the accumulation of protein chaperones and as such could be efficacious in the treatment of protein folding diseases." (PMID 21253609, 2011). "The importance in understanding HSF1 regulation is underscored by recent findings showing that pharmacological activation of HSF1 can increase protein chaperone expression and ameliorate cytotoxicity in models of protein folding disease." (PMID 21253609, 2011). "A yeast-based small molecule screen identifies a novel activator of human HSF1 and protein chaperone expression and which appears to alleviate the toxicity of protein misfolding diseases." (PMID 20098725, 2010). "The repressive function of HSF1 has become increasingly important in recent light of the targets repressed by HSF1 that contribute to disease, including inflammation, apoptosis, and protein misfolding diseases, such as Tau." (PMID 33208463, 2021). "In contrast to studies on HSF1, most studies on HSF2 have focused on protein misfolding diseases, aging, and the development of the embryo and sperm." (PMID 34917120, 2021).
acute myeloid leukemia (8 papers, 2018 to 2025). Acute myeloid leukemia (AML) is a group of neoplasms arising from precursor cells committed to the myeloid cell-line differentiation. "This was particularly the case in acute myeloid leukemia (AML), where nearly every gene overexpressed in the HSF1-dependent set of AML lines encoded a protein involved in translation (16 of 23 genes, enrichment P = 1 × 10−22)." (PMID 33328249, 2021). "Additionally, HSF1 was highly expressed in most of 21 leukemia cell lines, especially the acute myeloid leukemia cell line KG–1." (PMID 36069792, 2022). "MiR-34b enhances the apoptosis of acute myeloid leukaemia cells by decreasing HSF1 expression." (PMID 29898735, 2018). "Observed by us, the dual function of HSF1 seems to be tissue-specific: TCGA data analysis indicates that such an HSF1-dependent regulatory network may not exist in ER-negative breast cancer or acute myeloid leukemia." (PMID 36010586, 2022).
esophageal squamous cell carcinoma (8 papers, 2015 to 2024). Esophageal squamous cell carcinoma (ESCC) is a type of esophageal carcinoma (EC) that can affect any part of the esophagus, but is usually located in the upper or middle third. "Similarly, high HSF1 expression in stromal cells reflects poor prognosis in esophageal squamous cell carcinoma patients 134, suggesting that HSF1 may be involved in TME regulation." (PMID 37153737, 2023). "However, the clinical significance and biologic function of HSF1 in esophageal squamous cell carcinoma (ESCC) remain unknown." (PMID 26511079, 2015).
glioma (8 papers, 2009 to 2025). A benign or malignant brain and spinal cord tumor that arises from glial cells (astrocytes, oligodendrocytes, ependymal cells). "Our results indicate that MCL-1 degradation in an HSF1-independent manner is an essential step for the modulation of apoptotic cell death brought about by KRIBB11 in glioma cells." (PMID 34299435, 2021). "FoxM1 was also shown to be transactivated by HSF1, which promoted the survival of glioma cells under heat shock stress." (PMID 28148279, 2017). "While Huang and co-workers found that heat shock factor 1 (HSF1) regulates FOXM1 in glioma with changes in cell cycle proteins, including CDC20, our results provides the first direct evidence that FOXM1 maintains TICs via regulation the expression of CDC20." (PMID 25938542, 2015). "Interestingly then, HSF1 expression in glioma cell line U-343 MG-Cl2:6 with low NFIX expression was not sensitive to NFIX-siRNA." (PMID 19337383, 2009). "For the first time, this study revealed that Hsp70 and p-HSF1 (heat shock transcription factor 1) levels increased in glioma cells due to CER-mediated FASN inhibition, while no significant change was observed in Hsp60 and Hsp90 levels." (PMID 40133683, 2025). "In the present study, we demonstrated that an exclusive treatment with KRIBB11 effectively induces apoptosis in A172 glioma cells through acceleration of MCL-1 degradation, which is not accompanied by any alteration of HSF1 activity." (PMID 34299435, 2021).
osteosarcoma (8 papers, 2013 to 2025). A usually aggressive malignant bone-forming mesenchymal neoplasm, predominantly affecting adolescents and young adults. "After treatment with 50 μg/mL ALAPP, the level of Hsf1 expression was upregulated by about 50% in MC3T3 osteoblasts, but HSF1 expression remained almost unchanged in MG-63 osteosarcoma cells compared with untreated MG-63 cells." (PMID 37551169, 2022). "As the concentration of ALAPP was increased, the expression of Hsf1 in osteoblasts continued to rise until it reached the level of its homolog in the osteosarcoma, and then the proliferation of osteoblasts began to be gradually inhibited." (PMID 37551169, 2022). "High expression of HSF1 protein is significantly associated with aggressive disease and poor survival in CRC, ESCC, ccRCC and osteosarcoma." (PMID 30326922, 2018). "However, MG-63 osteosarcoma had preemptively activated HSF1 expression (by about 2-fold the expression of osteoblasts) to maintain normal survival of the osteosarcoma cells." (PMID 37551169, 2022). "Therefore, we speculate that ALAPP inhibits the expression of HSPs by inhibiting the activity of HSF1, thus inhibiting osteosarcoma cell proliferation." (PMID 37551169, 2022). "In U2OS osteosarcoma cells stably infected with KSHV, where a less robust HSF1 depletion was obtained, we confirmed that HSF2 overexpression increased ORF50 levels regardless of HSF1 silencing." (PMID 40245053, 2025). "When the activity of HSF1 was substantially inhibited by ALAPP, the osteosarcoma failed to express more HSF1, presumably due to the depleted potential expression pool." (PMID 37551169, 2022). "Without ALAPP treatment, the level of HSF1 expression in MG-63 osteosarcoma was about 2-fold the expression of Hsf1 in MC3T3 osteoblasts." (PMID 37551169, 2022). "It has been previously demonstrated that multidrug resistance of osteosarcoma U2-OS cells and hepatoma HepG2 cells was mediated by HSF1-dependent expression of the ABCB1 gene, but not by HSPs expression." (PMID 24165036, 2013). "ALAPP significantly upregulates the expression of HSF1 in MC3T3-EL osteoblasts, but not in MG-63 osteosarcoma." (PMID 37551169, 2022). "However, in MG-63 osteosarcoma cells, ALAPP failed to upregulate HSF1, and HSP90, CDK4, and AKT1 were downregulated to about the level seen in osteoblasts." (PMID 37551169, 2022).
colitis (7 papers, 2012 to 2023). Inflammation of the colon. "It has been demonstrated that a methyl-deficient diet is related to colitis progression and may induce the acetylation of HSF1 causing a dramatic decrease in chaperones under its regulation such as the binding immunoglobulin protein (BIP), HSP27 and HSP90." (PMID 37569505, 2023). "CD69 and HSF1 deficiency resulted in much more severe colitis in mice, which could be alleviated by the transplantation of CD69+ Tregs but not Tregs from CD69-knockout mice." (PMID 37064870, 2023). "HSF1 stabilization by PSIs efficiently induces more Tregs with higher potency to treat colitis and probably other autoimmune diseases involving Tregs deficiency." (PMID 37064870, 2023). "Stabilization of HSF1 by PSIs results in the efficient generation of Tregs with high potency to treat colitis and probably other autoimmune diseases involving Tregs deficiency." (PMID 37064870, 2023). "After inhibition of HSF1, more weight loss was observed in mice with DSS-induced colitis, which coincided with increased disease activity and tissue injury." (PMID 37064870, 2023). "Tenaka’s study indicated that disease activity, colon epithelial cells (CECs) apoptosis rate, and mucosal damage level of HSF1 overexpressed transgenic mice were significantly reduced compared with wild-type mice in DSS-induced mice colitis models." (PMID 35645809, 2022). "Chronic exposure to DSS in a model of azoxymethane (AOM)–DSS colitis-induced cancer led to HSF1-dependent activation of mTOR and increased glutaminolysis in cancer cells, and promoted tumor growth." (PMID 33288768, 2020). "When exposed to one course of dextran sulfate sodium (DSS) treatment (7 days), Hsf1 null mice displayed a more severe form of colitis compared to their wild-type (WT) counterparts." (PMID 33288768, 2020). "HSF2 has been shown overexpressed in the mucosa and sera of patients with UC, and, moreover, the expression correlates with the severity of the pathology; HSF1 together with HSP70 has been demonstrated to be protective during the induction of colitis or gastric lesions in mice." (PMID 37569505, 2023). "Thus, the results suggest that catalpol ameliorates colitis by modulating the miR132/SIRT1/HSF1 signaling pathway." (PMID 35883477, 2022). "This study confirmed that HSF1 is a protective factor for colitis at the genetic level." (PMID 35645809, 2022). "HSF1 plays a role in protecting against DSS-induced colitis." (PMID 22479607, 2012). "Genetic and chemical inhibition of HSF1 impaired CD69+ Treg differentiation and promoted the pathogenesis of colitis in mice." (PMID 37064870, 2023). "In contrast, HSF1 protein stabilized by inhibiting its proteasomal degradation promoted CD69+ Treg differentiation and alleviated colitis in mice." (PMID 37064870, 2023). "Moreover, catalpol decreased the levels of miR132 and the acetylation levels of Heat Shock Factor protein 1 (HSF1), while it increased SIRT1 protein levels in the rat colitis model." (PMID 35883477, 2022). "HSF1 knockout mice presented with more advanced colitis than wild-type mice, whereas transgenic mice overexpressing HSP70 or HSF1 were characterized by an amelioration of the symptoms, demonstrating the protective actions of HSP70 and HSF1 against gastrointestinal damage." (PMID 35883814, 2022). "In this work, we ask whether the protumorigenic role of HSF1 in colitis-induced cancer includes non-cell-autonomous effects on the TME." (PMID 33288768, 2020). "By increasing HSF1 protein levels, proteasome inhibitors (PSIs) such as MG132 and the anti-tumor drug bortezomib could promote the generation of CD69+ Tregs, thus offering a practical approach to generate potent iTregs for the treatment of colitis and probably other autoimmune diseases." (PMID 37064870, 2023).
amyloid (6 papers, 2014 to 2025). "The increased levels of Hsf1/B2 RNA processing in APP 6-month-old mice raised the question whether response to amyloid toxicity in hippocampal cells is connected with an Hsf1-mediated increase in B2 RNA processing." (PMID 33191914, 2020). "Furthermore, REMFS reverses PTMs that impair the normal function of IDPs, such as HSF1 and autophagy proteins, resulting in improved protein degradation, delayed aging, and potentially beneficial as an anti-amyloid therapy for human AD and neurodegenerative diseases." (PMID 41221473, 2025). "Given the sentence, "Hsf-1 affects podocyte markers NPHS1, NPHS2 and WT1 in a transgenic mouse model of TTRVal30Met-related amyloidosis," three entity relations, with relation type and biological context, were extracted by the context-based ABC model." (PMID 31017923, 2019). "Therefore, IT-induced higher expression of Hspb1 in AApoAII amyloidosis might be independent of HSF1 and regulated by other transcription factors." (PMID 35099007, 2022).
endometrial carcinoma (6 papers, 2015 to 2023). A malignant tumor arising from the epithelium that lines the cavity of the uterine body. "In fact, it was observed that high HSF1 expression in endometrial carcinoma was significantly associated with aggressive disease and poor survival, also among ERα-positive patients presumed to have a good prognosis." (PMID 31614463, 2019). "High HSF1 expression is linked to poor outcomes and disease progression in endometrial cancer." (PMID 37958341, 2023). "High levels of HSF1 expression have been reported in a number of cancers and high levels of nuclear HSF1 are associated with poor outcome in breast, hepatocellular and endometrial carcinoma among others." (PMID 33268814, 2021). "Overexpression of the HSF1 protein in particular has been linked with significantly lower survival in endometrial cancer patients and given our finding, this may have a correlation to the composition of the urogenital microbiome." (PMID 34739493, 2021). "Unfortunately, the role of HSF1 and estrogen receptors in endometrial cancer has yet to be fully elucidated." (PMID 37958341, 2023). "Previous studies have demonstrated that HSF1 is highly expressed in endometrial carcinoma and is closely related to endometrial invasion, which leads to a poor prognosis in estrogen receptor-positive tumors." (PMID 34107992, 2021).
glioblastoma (6 papers, 2017 to 2025). The most malignant astrocytic tumor (WHO grade IV). "An mTORC2/Akt/HSF1/HuR feed-forward loop, promoting Rictor via HSF1-induced HuR activity, is furthermore associated with increased growth rates and aggressiveness in glioblastoma." (PMID 40287736, 2025). "We compared HSF1 protein levels between the standard ML and SP-forming culture conditions for 72 h in A172 glioblastoma cells." (PMID 28241425, 2017). "These sites may in turn respond to mTORC2 signaling, as mTORC2 activates heat shock transcription factor HSF1, which induces HuR activity in glioblastoma (GBM) models." (PMID 38270460, 2024). "Moreover, the TSP-4 secreted by CAF can improve the transcription level of HSF1 in glioblastoma cells and upregulate lncRNA DLEU1 to confer glioblastoma ferroptosis resistance." (PMID 37784082, 2023). "We hypothesized that BIS plays a key role in stemness-related properties via HSF1 regulation and that BIS or HSF1 depletion combined with TMZ treatment would induce apoptosis in SPs of the glioblastoma cell line A172." (PMID 28241425, 2017). "Even though the effect of HSF1 depletion on the TMZ sensitivity is not synergistic but only additive, our results provide the possibility that targeting HSF1 could be used as an adjunct to conventional TMZ treatment for glioblastoma to diminish the dose of TMZ as well as its toxic side effects." (PMID 28241425, 2017). "HSF1 also directly interacts with BIS, although it is still unclear whether this interaction is critical in the regulation of glioblastoma stem cells (GSCs)." (PMID 28241425, 2017).
invasive breast carcinoma (6 papers, 2017 to 2025). A carcinoma that infiltrates the breast parenchyma. "HSF1 mRNA expression was upregulated in various cancer types, including breast invasive carcinoma (BRCA), colon adenocarcinoma (COAD), head and neck squamous cell carcinoma (HNSC), and prostate adenocarcinoma (PRAD) among others." (PMID 39243039, 2024). "In patients with invasive breast cancer, ErbB2 is positively correlated with the HSF1/LDHA axis." (PMID 40593465, 2025). "High HSF1 nuclear levels (estimated by immunohistochemistry in patients with invasive breast cancer at diagnosis; in situ carcinomas and stage IV cancers were excluded from the outcome analysis) were previously associated with decreased survival specifically in ER-positive breast cancer patients." (PMID 34783649, 2021).
lymphoma (6 papers, 2011 to 2023). A malignant (clonal) proliferation of B- lymphocytes or T- lymphocytes which involves the lymph nodes, bone marrow and/or extranodal sites. "Although an additional HSF1 deficiency does not prolong tumor-free survival, it shifts tumor development from lymphomas to testicular carcinomas and soft tissue sarcomas." (PMID 24467529, 2014).
non-small cell lung carcinoma (6 papers, 2014 to 2025). A group of at least three distinct histological types of lung cancer, including non-small cell squamous cell carcinoma, adenocarcinoma, and large cell carcinoma. "Previous studies showed that low celastrol and erastin concentrations activated HSF1 to protect cells from proteotoxic stress, and HSF1 knockdown further enhanced non-small cell lung cancer cell death in vitro and vivo." (PMID 37351671, 2023). "A non-nuclear Hsf1 is also observed in non-small cell lung cancer line cells, in which Hsf1 associates with and disables the anti-apoptotic membrane-bound Ralbp1 protein." (PMID 25078989, 2014).